IL1B (interleukin 1 beta)
Diseases named in the same sentence as IL1B in open-access papers (continued):
Sharing a sentence is not in itself a finding about the gene and the disease.
tumor (continued). "As such, the improved chemosensitivity associated with NLR attenuation in our preclinical models suggest that combining chemotherapy with therapeutic strategies to mitigate neutrophil-stromal-tumor cell IL-1β/IL-6/STAT-3 signaling in PDAC patients may be advantageous." (PMID 36107485, 2022). "Therefore, IL-1β-mediated-MMP-3 may contribute to malignant tumor processes by creating a suitable microenvironment for tumor development and progression." (PMID 36445856, 2022). "To determine whether the anti-tumor effect of the active ingredients of YFBP is associated with the regulation of the expression of the inflammatory mediator, we assessed the gene expression of TNFα, IL-1β, and IL-6." (PMID 36353478, 2022). "However, cytokines released by tumor cells, such as G-CSF, IL-1β, IL-6, or tumor necrosis factor (TNF), have been proposed to prolong neutrophil lifespan, indicating that neutrophils may have a significant impact on cancer." (PMID 35784290, 2022). "However, IL1B was found to be upregulated in a variety of tumours and related to poor prognosis." (PMID 35083859, 2022). "Notably, both IL-1β and IL-18 exert dual effects in tumor progression." (PMID 35739593, 2022). "Interestingly, M2 infiltrated highly in the high CRG_score group and subtype B. In the TME, inflammatory and cytotoxic effector functions of NK cells are weakened by a number of cytokines such as IL-23 and IL-1β, where NK cells are called tumor-infiltrating natural killer cells (TINKs)." (PMID 36684237, 2022). "Furthermore, IL-1β could promote osteolytic activity and induce the dormancy, angiogenesis, and reactivation of tumor cells in PCa." (PMID 36237303, 2022). "Whilst there is increasing evidence suggesting differential roles of IL1β in immune cell regulation of tumour growth in the bone and soft tissue microenvironments, suitable samples for further analysis of this hypothesis using the small molecule inhibitors tested in the current study were not taken." (PMID 36230739, 2022). "Additionally, IL-6 plays a role in the recruitment of immune cells within the tumor microenvironment, thereby stimulating the production of other pro-inflammatory cytokines, including IL-1β, IL-8, and TNFα, thus providing a link between the inflammatory process and tumor progression." (PMID 35053592, 2022). "Notably, IL1β also plays beneficial roles in the initiation of anti-tumor immunity in TME." (PMID 35432318, 2022). "We then performed automated H-score analysis for TLR2 and IL-1β on identical tumor regions from consecutively stained sections and found a significant positive correlation between TLR2 and IL-1β expression, suggesting that TLR2 may regulate expression of the SASP in LUAD epithelium." (PMID 36351380, 2022). "The antitumorigenic immune components of tumor microenvironment are natural killer (NK) cells, dendritic cells (DC), cytotoxic T lymphocytes (CTLs), and M1 tumor-associated macrophages (M1 TAMS) secreting mainly proinflammatory cytokines like IL-1β, IL-1α, IL-6, IFNγ, TNFα etc.." (PMID 36496977, 2022). "Thus, AIM2 in NSCLC exerts tumor‐promoting effects in an inflammasome‐dependent manner and regulation of mitochondrial dynamics, presumably triggering an IL‐1β/STAT3 response by the nuclear factor‐κB (NF‐κB)/COX‐2/HIF‐1α pathway and contributing to the MAPK/ERK pathway activation." (PMID 34014039, 2021). "Moreover, blocking IL-1β can synergize with anti-PD-1 for tumour abrogation." (PMID 35006432, 2021). "However, at a high-level IL-1β released by tumor cells promotes tumor progression and metastasis." (PMID 34577552, 2021). "Inhibitors of TNFα and IL-1β are currently used in the clinic in the treatment of inflammatory diseases and may have many advantages when introduced to cancer therapy at the stage of tumor diagnosis." (PMID 33806906, 2021).
tumor (continued). "Transactivation p73β (TAp73β) has been shown to directly activate the positive transcription of caspase-1 and upregulate the expression of pro-IL-1β mRNA and IL-1β protein, and thus may be important for the regulation of the inflammasomes and inflammation in tumor." (PMID 34602858, 2021). "In tumor lesions, inflammasomes recognize pathogen-related molecular patterns or host-derived danger signal molecules to recruit and activate the pro-inflammatory protease caspase-1, which could cleave pro-IL-1β into bioactive IL-1β." (PMID 34625124, 2021). "In addition, CM from IL1β-treated fibroblasts induces the overexpression of Cyclin D1 and cMyc, which might help explain how IL1β-soluble targets influence the cell-cycle progression and chemoresistance observed in tumor cells, when treated with L-OHP." (PMID 34066976, 2021). "Therefore, downregulation of IL1B may decrease carcinogenesis and metastasis, but may also be able to block adaptive anti-tumor responses." (PMID 33690729, 2021). "Further macrophage subsets were identified based on their high expression of CD68, CD163, and MRC1 (encoding CD206), which could be denoted as resident tissue macrophages and segregated into normal colon epithelial tissue (NLRP3+ and phospholipid transfer protein PLTP+) or tumor tissue (IL1B+)." (PMID 34572013, 2021). "The DEGs enriched in TAMs were related to pathways such as extracellular matrix disassembly, response to hypoxia, positive regulation of cholesterol efflux and response to TNF and IL1B, implying that they may promote cell migration, angiogenesis, tumor progression and inflammation." (PMID 33144684, 2021). "One study describes IL-1β to trigger the development of osseous metastases, whereas other studies suggest that IL-1β could rather impede the colonization of metastasis inducing tumor cells." (PMID 33946741, 2021). "Overexpression of IL‐1β in TME could drive tumor immune resistance." (PMID 34382349, 2021). "However, both tumor-inhibiting and tumor-promoting effects have been reported for IL-1β." (PMID 34943147, 2021). "This implies that GSDME-induced pyroptosis is, in principle, not linked to the liberation of IL-1β and may thereby be associated with improved anti-tumor effects." (PMID 34490126, 2021). "Surgical resection of the primary tumour alongside IL-1B targeting may be appropriate." (PMID 34290237, 2021). "Thus, colonization and secondary tumor formation are inhibited by sustained IL-1β." (PMID 33686176, 2021). "The effect of long-term use of antibiotics on IL-1β release by tumor cells is largely unknown." (PMID 34577552, 2021). "Furthermore, IL-1β is known to contribute to the metastasis and aggressiveness of neoplasms." (PMID 34359685, 2021). "Blocking the IL-1β/IL-6 network in TME could halt tumor progression." (PMID 34379689, 2021). "Here, our finding showed that DPP-4i promoted caspase-1-dependent processing of IL-1β and IL-33 by activating NF-кB–NLRP3 activation, indicating that DPP-4i may reprogram tumor microenvironment by promoting 4T1 cells-derived IL-1β and IL-33 via NF-кB–NLRP3 pathway." (PMID 34631556, 2021). "In BC, it may act as a tumor suppressor by recruiting immune effector cells when it is expressed at higher levels in the tumor than in the adjacent healthy tissues, while IL-1β, TNFα, IL-6, and interferon (IFN)γ upregulate CCRL2." (PMID 33670492, 2021). "It is also important to consider that the in vivo models used in this work allow for a rapid development of primary tumour growth and bone metastasis, and therefore do not take into account the role of IL-1B in the context of chronic inflammation that associates with tumour development." (PMID 34290237, 2021). "However, we found IL1β expression in the group of cRCC, with excellent outcome of disease and not in the group of tumours with increased cell motility leading to high risk of postoperative metastatic growth." (PMID 34433833, 2021).
tumor (continued). "The upregulation of tumour inflammasome-derived IL-1β to a certain threshold has been shown to suppress the growth of EBV-associated NPC cells by promoting an influx of neutrophils, while depletion of these neutrophils significantly diminishes the antitumour effects of IL-1β." (PMID 33918087, 2021). "In addition, IL-1β is a pro-inflammatory cytokine that has previously been shown to have tumoricidal activity and repress tumor growth; thus, its increased gene expression may contribute to the anti-proliferative effects of carnosine." (PMID 33809496, 2021). "This implies that IL-1B may have different effects on neutrophil recruitment in bone versus other sites, which is concordant with our data that microenvironment-derived IL-1B promotes the recruitment of anti-tumour neutrophils to the primary tumour site, but reduces recruitment to bone." (PMID 34290237, 2021). "Additionally, our data suggest that although inhibition of IL-1B has the potential to reduce bone metastasis, primary tumour growth may increase." (PMID 34290237, 2021). "Thus, we interpret IL-1β as a stress signal indicating the activation of the local immune system, which may assist to control tumor progression." (PMID 33946741, 2021). "While several studies have demonstrated IL-1β to generally promote both intrinsic and extrinsic properties of tumorigenesis, including angiogenesis and immune evasion, it is important to also recognize that a role for IL-1β has been described in promoting anti-tumor immunity in specific contexts." (PMID 34638239, 2021). "Additionally, NLRP12 is significantly increased, which may promote tumor growth by triggering NF‐κB and IL‐1β signaling." (PMID 34014039, 2021). "In addition, IL-1β-stimulated tumor cells displayed enhanced migratory and invasive capabilities." (PMID 32547321, 2020). "Interestingly, on the contrary of nuclear RORγt expression, both IL-1β and IL-23 were correlated to more aggressive clinic and pathological features that included large tumor size, presence of distant metastasis at diagnosis and requirement of higher cumulative dose of RAI." (PMID 32139737, 2020). "Consequently, this highlights the importance of IL-1β as a master cytokine in tumor progression and thus could be a potential novel checkpoint for therapeutic targeting." (PMID 32784928, 2020). "Furthermore, similar to our data, an earlier study demonstrated the upregulation of IL-1B in tobacco and betel quid-mediated OSCC; IL-1B promotes proliferation of dysplasia of oral cells, thus triggering oncogenic cytokines as promoters of tumor aggressiveness." (PMID 32961854, 2020). "However, many recent studies have shown that other intra-tumor cells can produce IL-1β." (PMID 33261061, 2020). "Moreover, we demonstrated that IL1β secreted by tumor cells is required for NF-κB activation in SCs, which could be abolished by the addition of anti-IL1β antibodies to the culture medium of SCs." (PMID 32308766, 2020). "In supernatants derived from RANK+/+ tumor acini, many cytokines were upregulated including stromal cell-derived factor-1α, macrophage inflammatory protein-1α, interleukin (IL)-1α, stem cell factor, tumor necrosis factor-α, IL-13, macrophage colony-stimulating factor, IL-10, IL-4, IL-17, and IL-1β." (PMID 33303745, 2020). "Therefore, we could suggest that the suppressive activity of tumor-infiltrating PMN-MDSCs in CRC is positively regulated by IL-1β/NF-κB signaling pathway." (PMID 31941522, 2020). "Also, the levels of IL-1β and IL-6 decreased, but the level of IL-10 increased, which may reduce the cytokine-induced tumor immunosuppressive activity, cancer progression and cancer cachexia syndrome." (PMID 33013406, 2020). "Similarly, NLRP3 expression levels are also correlated with the tumor size, lymph node metastatic status and IL-1β expression in oral squamous cell carcinoma (OSCC), and downregulating NLRP3 expression markedly attenuates the proliferation, migration, and invasion of OSCC." (PMID 33613533, 2020).
tumor (continued). "We also noted the possibility in vivo that other cells, except tumor cells and LSECs, may induce IL‐1β expression such as kupffer cells and stellate cells, which constitute a positive loop to enhance sinusoidal disruption and facilitate liver metastasis of GBC cells." (PMID 33252861, 2020). "In addition to an altered metabolic phenotype, inflammation has been reported to play a significant role in the progression and treatment response of OAC tumours, whereby elevated levels of pro-inflammatory mediators such as LIF, C3a, C4a and IL-1β have been associated with poor treatment response." (PMID 32694701, 2020). "Stimulate microglial cells to secret IL-1β which could induce tumor angiogenesis." (PMID 33013829, 2020). "The tumor-promoting effect of IL-1β might be mediated through multiple mechanisms." (PMID 31649305, 2020). "Therefore, the priming of IFN‐γ‐producing CD8+ T cells by dying tumor cells fails in the absence of a functional IL‐1 receptor 1 and in Nlrp3‐deficient or caspase‐1‐deficient mice unless exogenous IL‐1β is provided." (PMID 33179413, 2020). "Thus, to examine whether there are common tumor-promoting factors between parent and resistant cells that enhance neutrophil survival, we tested the expression of pro-inflammatory factors such as IL-1β, CCL2, CCL3, CCL4, IL23, and iNOS in neutrophils." (PMID 33049964, 2020). "However, some anti-tumor effects of IL-1β have been reported." (PMID 33194755, 2020). "In addition, ATP may fuel a direct antitumor immune response by depleting Treg cells via P2X7R-mediated cytotoxicity or via stimulation of DCs, thus triggering IL-1β release and potentiating tumor antigen presentation to CD4+ and CD8+ lymphocytes." (PMID 33212982, 2020). "Moreover, other studies have shown how IL-1β is responsible for enhancing tumor metastasis." (PMID 33015196, 2020). "Importantly, we found that in CD68High tumors, hypoxia is associated with the expression of pro-inflammatory cytokines, such as IL1B, IL6, and TNF, previously associated with the recruitment of other anti-tumor immune cells, suggesting the establishment of a pro-inflammatory TM." (PMID 32231135, 2020). "Thus, the prevalence of stroma, or tumor-derived gPTGS2, could mirror the strong or weak response to the presence of IL1β in CRC tissues." (PMID 32168749, 2020). "Therefore, our findings demonstrate that DHA may act as a RalB inhibitor to regulate the crosstalk between autophagy and IFI16/caspase-1 inflammasome, which inhibits IL-1β production in tumor microenvironment." (PMID 32577124, 2020). "In this study, we aimed to study whether IL-1β could enhance the stemness traits of tumor cells." (PMID 32547321, 2020). "Furthermore, accumulating data demonstrate the promoting role of IL1B in tumor development." (PMID 33168816, 2020). "However, we also observed IL‐1β expression by some HPV‐positive tumour cells, suggesting that loss of IL‐1β in vivo is not absolute." (PMID 30191960, 2019). "This liposome could significantly increase the cytokine rations of IL-12/IL-4, IL12/IL-1α, IL-12/IL-1β, IFN-γ/IL-6, IFN-γ/IL-1α, and IFN-γ/IL-1β by 1.18–3.14-fold, (P < 0.05), thus favoring the balance of Th1 and Th2 cells to stimulate antitumor effects in the tumor microenvironment." (PMID 31915707, 2019). "Moreover, inflammation in the tumor microenvironment mediated by IL-1β is hypothesized to play a major role in cancer invasiveness, progression, and metastasis." (PMID 31174565, 2019). "These adipocytes located near the tumor are called “cancer-associated adipocytes” (CAA) and are characterized by a loss of lipid content, a decrease in late marker expression of adipogenesis, and an overexpression of inflammation markers (IL-6, IL-1β) and proteases (MMP-11, PAI-1)." (PMID 31756890, 2019).
tumor (continued). "Interestingly, while in the primary tumour knockout of CAF-derived IL-1β resulted in attenuated recruitment of the granulocytic fraction (CD11b+Ly6G+Ly6Clow), in the metastatic microenvironment CAF-derived IL-1β was important for the recruitment of the monocytic fraction (CD11b+Ly6ChighLy6G−)." (PMID 31558756, 2019). "Furthermore, it has been shown that the transfected 4T1 tumor cells constitutively expressing IL-6 induced expansion of MDSCs and restored MDSCs accumulation in tumor-bearing IL-1 receptor knockout mouse, suggesting that IL-6 is likely to be a relevant IL-1β downstream mediator." (PMID 30998767, 2019). "Therefore, we hypothesize that radiation-activated NFκB signaling stimulates tumor progression by modulating post-irradiation cytokine expression, such as IL-1β." (PMID 31766169, 2019). "Sustained IL-1β may promote tumor propagation by different mechanisms." (PMID 31766169, 2019). "Interestingly, HERV-K positive EVs concentrations were significantly associated with a reduced expression of IL1-β and mpx, supporting our hypothesis that HERV-positive EVs may act as immunomodulators in tumor progression." (PMID 31357477, 2019). "Thus, in our system, tumor cell-derived ASC might also contribute directly through unknown mechanisms to NF-κB activation for pro-IL-1β production." (PMID 30760333, 2019). "Finally, we assessed if inhibiting microenvironmental IL1β or tumour cell Wnt signalling could prevent bone metastases in vivo." (PMID 31676788, 2019). "In addition, IL-1β could lead to an immunosuppressive microenvironment in both primary tumours and metastatic distant organs (unpublished data)." (PMID 31588122, 2019). "IL-1β, a pro inflammatory cytokine that participates to both cytotoxic response and tumoral angiogenesis, was the only cytokine that was significantly secreted in higher amount in the tumor (52.3 ± 14.8 pg/ml) compared to the adjacent healthy tissue (4.65 ± 2 pg/ml)." (PMID 31105699, 2019). "Colonization and subsequent proliferation of ΔppGpp S. typhimurium within tumor tissues induces infiltration of immune cells, such as neutrophils, macrophages, and dendritic cells, which then secrete pro-inflammatory cytokines, such as IL-1β, which contribute to anti-cancer efficacy." (PMID 31754923, 2019). "Moreover, our data suggest that the mechanism by which CAF-derived NLRP3/IL-1β facilitate tumour growth and metastasis is by altering the immune cell milieu towards a tumour-tolerating phenotype, and by enhancing endothelial cell adhesiveness and cancer cell invasiveness." (PMID 31558756, 2019). "Studies demonstrate that tumor colonization by bacteria can induce proinflammatory reactions involving elevated expression of IL-1β, TNF-α, and IFN-γ, as well as NK and T-cell activation; therefore, a combination of ICB and bacterial therapies may overcome host resistance." (PMID 31827064, 2019). "Interestingly, IL-1β may promote tumorigenesis and tumor invasion, and the blockade of the IL-1 receptor by an IL-1R antagonist was shown to improve the anti-tumor effect of chemotherapy." (PMID 31156650, 2019). "Furthermore, the MDSCs may promote γδT17 polarization by secreting IL-23 and IL-1β, which further mediate tumor immune tolerance." (PMID 32063899, 2019). "Besides Il-1β and its downstream cytokines, there are other mechanisms which may participate in the promotion of stem cell-like properties in tumor cells by MSCs." (PMID 29670904, 2018). "Furthermore, an augmentation of lung metastasis from A375M tumor cells could be observed after (IV) injection of IL-1β." (PMID 30042333, 2018). "The increased synthesis of IL-1β, IL-6 and IL-8 can induce the expression of other proinflammatory genes including COX-2 (ciclo-oxigenase-2) and CCL20 by the adjacent fibroblasts and attract, among other inflammatory cells, tumor-associated macrophages (TAM) and Th17 cells." (PMID 29976244, 2018).